TIMP2 (TIMP metallopeptidase inhibitor 2)
Diseases named in the same sentence as TIMP2 in open-access papers (continued):
Sharing a sentence is not in itself a finding about the gene and the disease.
tumor (continued). "We hypothesized that the production of TIMP2 from virus infected cells should bind and inhibit excess extracellular MMPs and thereby inhibit tumor progression through both MMP-dependent and MMP-independent pathways." (PMID 22022379, 2011). "TIMP-2 upregulation of NF-κB activity may inhibit tumor growth in the early stage because other data suggest a dual function of NF-κB during tumor progression." (PMID 21152266, 2010). "Study using breast cancer samples demonstrates that the expressions of MMP-1, MMP-2, MMP-3, MMP-9, urokinase-type PA, and tissue-type PA, and inhibitors (TIMP-1 and TIMP-2) were stronger or equivalent in tumor cells than in fibroblasts or inflammatory cells within the tumor section." (PMID 21152266, 2010). "Our data indicate that elevated endogenous TIMP-2 can up-regulate the NF-κB activity, which may inhibit tumor growth in the early stage." (PMID 19627587, 2009). "Their studies revealed further elevated MMP2, MMP3, and TIMP2 concentrations from patients after tumour resection, which might function as a predictive value for early detection of tumour recurrence." (PMID 16901349, 2006). "Similar results were reported using immunohistochemical studies of TIMP2 in invasive tumours." (PMID 15083203, 2004). "There was however an increase in MMP-2/TIMP-2 ratio in tumour compared to normal." (PMID 11401321, 2001). "Positive expression of TIMP-2 (a) in basement membranes and (b) diffusely in stroma with (c) subglandular enhancement was found significantly (P < 0.01, P < 0.05, P < 0.05) more often in localized tumours than in tumours with regional or distant metastases." (PMID 9310250, 1997). "MMPs (e.g., MMP-2, MMP-9) are involved in extracellular matrix degradation, with their overexpression linked to tumor invasion and metastasis, while TIMPs (e.g., TIMP-1, TIMP-2), as natural inhibitors of MMPs, may exacerbate disease progression when their expression is imbalanced." (PMID 40332776, 2025). "To determine whether TAM-derived exosomes are responsible for tumor progression via TIMP2-regulated VM in vivo, we orthotopically implanted 786-OLuc cells into nude mice to establish the mouse model and divided mice into two groups based on different treatments." (PMID 35443741, 2022). "Therefore, there is a need to evaluate the role of TIMP-2 in tumor cell resistance to 5-Fu therapy." (PMID 35022331, 2022). "We propose that future studies into TIMP2 activity in the TME may reveal potential avenues for the use of TIMP2, or similar biological agents, as a cancer biotherapeutic that may offer viable treatment options in combination with other directed anti-tumor therapies." (PMID 31882975, 2019). "Therefore, elevated miR-130b expression may increase the permeability of surrounding vascular endothelial cells via downregulation of TIMP-2 levels in the tumor microenvironment, leading to subsequent tumor cell intravasation in NSCLC." (PMID 31061410, 2019). "Moreover, TIMP2 could prevent the activation of tyrosine kinase receptors in tumor cells, including focal adhesion kinase, AKT and epithelial growth factor receptor, which played key roles in tumor migration and growth." (PMID 31703725, 2019). "Furthermore, activation of TIMP2 expressing monocytes in the primary tumour could present a potential therapeutic opportunity to suppress cell invasion in PDAC." (PMID 31836008, 2019). "Moreover, we indicated that serum levels of MMP-2 and classical tumor markers were lower, whereas TIMP-2 concentrations – higher in PC who alive in comparison to those who died because of PC, however the significant difference was found only for CEA concentrations (p = 0.004)." (PMID 30719232, 2019).
tumor (continued). "According to the function related to inflammation, angiogenesis, apoptosis, fibrosis and tumor growth, which are closely associated with either the development of DR or VEGF signaling, we were interested in following candidate proteins: APOC1, SERPINA5, TIMP2, and KRT1." (PMID 29541006, 2018). "The administration of exogenous recombinant TIMP-2 may sustain normalization of tumor microenvironment by keeping the actions of metzincins under check which may support intact functional ECM and vascularization and may also facilitate a broader window for chemotherapy treatment response." (PMID 29393911, 2018). "The marked TIMP-2 staining observed in the hereditary group may be due to an earlier diagnosis of the disease in these patients due to molecular screening in contrast to a more advanced tumor at the time of diagnosis in the sporadic group of patients." (PMID 24527080, 2014). "Hence contrary to the previously documented antitumor effects of TIMPs; TIMP-2 immunoexpression could have a tumor-promoting role in tumor recurrence and poor prognosis." (PMID 24591757, 2014). "However, HSA/TIMP-2 treatment had a significant anti-proliferation effect in tumor cells in vivo." (PMID 22545131, 2012). "In addition, group 2 showed a significantly higher percentage of tumours positive for TIMP-1, MMP-9 and -11 in the tumour cells; as well as a significantly higher percentage of tumours positive for TIMP-2, TIMP-3, MMP-9, -11, -13 and -14, in fibroblastic cells." (PMID 17848954, 2007). "VARGG accurately reveals the spatial organization of tumors and identifies key genes related to tumor progression and immune microenvironment (VEGFA, CD74, SPP1, IGFBP5, TIMP2, EMP1, THY1)." (PMID 41275376, 2025). "NDs with a higher sp3/sp2 carbon ratio effectively reduce the proangiogenic activity of tumor cells by downregulating key cytokines such as IL-6, IL-8, TIMP-1, TIMP-2, ANG, and ANGPTs." (PMID 40804455, 2025). "Among them, we selected seven genes associated to cell proliferation and apoptosis that resulted downregulated in tumor samples: BTG1, CCNG1, DMD, EDG1, SEMA3G, SYNPO2, TIMP2." (PMID 39984959, 2025). "In contrast, members of the TIMP family, mainly TIMP2, have long been recognized as modulators of MMP activities, thus regulating tissue homeostasis, and suppressing both primary tumor growth and metastasis formation." (PMID 38607010, 2024). "As the result shown, MPS with high expression of TIMP1 were distributed more within the tumor, while MPS with high expression of TIMP2 were distributed more in stroma." (PMID 38408082, 2024). "This was consistent with the spatial transcriptome data we analyzed, which showed that MPS with high expression of TIMP1 were distributed more within the tumor, while MPS with high expression of TIMP2 were distributed more in stroma." (PMID 38408082, 2024). "In a group of patients with stages IB–IV EC (n = 11), TIMP2, CSF3, ENPP2, and SERPINF1 were significantly down-regulated in tumour tissue, by 4.9-fold, 9.6-fold, 10.2-fold, and 9.2-fold, respectively." (PMID 37509322, 2023). "Due to the dual nature of TIMP-2, small shifts in the MMP-2/TIMP-2 balance can facilitate tumour progression and influence disease recurrence." (PMID 37932474, 2023). "KLF4 also inhibited the migration and invasion of tumor cells by suppressing biological enzymes, including TIMP-1 and TIMP-2." (PMID 37031197, 2023). "This in vivo study showed that, in contrast to propofol, sevoflurane exposure resulted in bigger ex vivo tumour size, shorter survival time, higher HGF and HIF1α expression, and lower TIMP-2 expression than propofol injection." (PMID 35953652, 2023). "TIMP2 is a known inhibitor of MMP activity and tumor growth that has been shown to be reciprocally downregulated with MMP2 upregulation." (PMID 36765529, 2023). "Tumor environment (TME) was coincident with increasing levels of active MMP expression, which was overwhelmed by TIMP2, resulting in tumor promoting functions." (PMID 36304987, 2022).
tumor (continued). "We assessed the expression levels of candidate invasion-specific protein biomarkers CTSK, MMP9, MMP2, TIMP2, and PTTG1 by immunohistochemical staining in paraffin-embedded NFPA tumor tissues." (PMID 36052250, 2022). "TIMP-2 regulates MMP-9 and MMP2 expression at the protein and mRNA levels and prevents further metastasis of tumor cells." (PMID 35770085, 2022). "Our findings revealed a new picture of the interaction between tumor cells and TAMs: specific miRNAs transferred from macrophage-derived exosomes (MDEs) to RCC cells downregulate TIMP2 expression and promote VM and cell invasion in RCC." (PMID 35443741, 2022). "Both TIMP2 and EYA1 proteins have been identified as tumour promoters in various cancers inducing cell migration and tumour metastasis." (PMID 36397137, 2022). "In the invasive tumor group there were two significant correlations: first between MMP-1and MMP-2 expression (rho = 0.306, p = 0.031) and second between TIMP-2 and MMP-9 expression (rho = 0.464, p = 0.001)." (PMID 36551933, 2022). "After the xenograft tumour was established in mice, the tumour volume was determined and the expressions of METTL3, miR‐589‐5p, MMP‐2, TIMP‐2, E‐cadherin, N‐cadherin and Vimentin in tumour tissue were detected by RT‐qPCR and Western blotting." (PMID 35348293, 2022). "We observed expression by tumor cells of thrombospondin (THBS1) and tissue inhibitors of metalloproteinases (TIMP1 and TIMP2), secreted factors involved in extracellular matrix remodeling." (PMID 36028490, 2022). "In the invasive tumor group we found two significant positive correlations: first between MMP-1 and MMP-2 expression (rho = 0.306, p = 0.031) and second between TIMP-2 and MMP-9 expression (rho = 0.464, p = 0.001)." (PMID 36551933, 2022). "To further confirm the role of TIMP2 in RCC clinical samples, we detected its expression via immunohistochemistry (IHC) in 23 pairs of human clinical samples derived from ccRCC tumor tissues and adjacent normal tissues." (PMID 35443741, 2022). "Thus, high-grade tumor budding and expression by MICs of MMP-9, -11, -14, TIMP-1, or TIMP-2 were associated with a poor prognosis in all cases, whereas the association of low tumor budding count and the non-expression of either MMPs or TIMPs was associated with a better outcome." (PMID 33669393, 2021). "It has been reported that tissue inhibitor of metalloproteinases-2 (TIMP-2) bound to MT1-MMP and activated the ERK1/2 and AKT pathway, thereby regulating tumor apoptosis and growth." (PMID 34297054, 2021). "It has been shown that TIMP2 inhibits in vivo VEGF-induced angiogenic responses and primary tumor growth of human lung xenografts, as well as inhibiting metastasis in an orthotopic, murine triple-negative breast cancer (TNBC) model." (PMID 34638439, 2021). "The diagnostic sensitivity of TIMP-1 was higher (61%) than that of the serum levels of other biomarkers (MMP-9—55%; TIMP-2—59%, MMP-2—46%) as well as the classical tumor markers (CEA and CA 19-9), and increased in combined use with CEA." (PMID 34071492, 2021). "The expression of TIMP-1 and TIMP-2 was detected in stromal cells, and TIMP-3 expression in tumor epithelial cells, in the infiltrative area." (PMID 34204372, 2021). "In this study, miR-200b targets TIMP-2, miR-200c targets FN1 and both miRNAs act as tumor suppressor miRNAs." (PMID 34298609, 2021). "A previous study has indicated that the dynamic balance between TIMP-2 and MMP-2 can affect tumor invasion and metastasis." (PMID 33027062, 2020). "As a result, it was expected that a high level of TIMP-2—by inhibiting MMP-2 and its procancerous activity—will result in inhibition of cell growth and tumor spread, improving patient prognosis." (PMID 32751899, 2020). "Tumor tissue was analyzed by immunohistochemistry for expression of uPA, uPA receptor, MMP-2, MT1-MMP and TIMP-2." (PMID 32121654, 2020).
tumor (continued). "The Oncomine database was used in our analysis and the mRNA levels of COL8A1, TIMP2, and GPR124 were higher in tumor tissues compared with normal tissues." (PMID 32095347, 2020). "Earlier studies in tumor cells also show that MMP-7 is a potential activator of pro-MMP-2, through competitively binding to the TIMP-2 from MMP-2/TIMP-2 complexes, leading to the release of functional MMP-2." (PMID 32630493, 2020). "LncRNAs such as lnc ADAMTS9-AS2, MT1JP, and GAS5 act as tumor suppressors in lung cancer through lncRNA/miRNA ceRNA networks, which regulate the expressions of well-known tumor suppressors such as PTEN and TIMP2." (PMID 33412752, 2020). "Nevertheless, LCL-DOX inhibited statistically significant (by 40–60%) the expression of proteins involved in the anti-tumor response: TIMP-1, TIMP-2, IFN-γ, MIG, PF-4, and IL-12p70." (PMID 32340166, 2020). "The area under ROC curve (AUC) for TIMP-2 was larger than for MMP-2, but lower than for classical tumor markers." (PMID 30719232, 2019). "Therefore, high expression of miR-130b may affect the overall survival of patients with NSCLC by targeting TIMP-2, which in turn promotes cancer cell invasion and enhances the functions of endothelial cells and myeloid-derived suppressor cells in tumor tissues." (PMID 31061410, 2019). "Tissue inhibitor of matrix metalloproteinase 2 (TIMP2), which is the special member of the TIMP family and can regulate many physiological progression such as tumor growth, metastasis, and angiogenesis through matrix metalloproteinases (MMPs)." (PMID 31383784, 2019). "MiR-373-3p mimics reduced lncRNA-LET-induced up-regulation of DKK1 and TIMP2 levels, and attenuated lncRNA-LET-mediated anti-tumor effects in ccRCC cells." (PMID 31768131, 2019). "In other studies, plasma levels of LCN2/matrix metallopeptidase 9 complex, MMP2, TIMP1, TIMP2 and TIMP3 were correlated to tumor size, lymph node involvement, tumor differentiation and prediction of tumor stage and T status in patients affected with HNSCC." (PMID 31014274, 2019). "Glycosaminoglycan, CaG can strengthen ECM by increasing activity of TIMP-2 and adhesion activity on collagen known to inhibit changes of ECM, leading to tumor cell invasion and progression." (PMID 30611221, 2019). "Previous studies have shown that TIMP2 interacted with MT1-MMP complexes, activated the Akt pathway, and inhibited tumor cell apoptosis." (PMID 31182988, 2019). "The AUC for TIMP-2 (0.6037, p = 0.013) was higher than for MMP-2 (0.5624, p = 0.146), but lower than AUC for classical tumor marker (CA 19-9 – 0.8583, p < 0.001; CEA – 0.8790, p < 0.001) in the differentiation between PC patients versus healthy subjects." (PMID 30719232, 2019). "Transcriptional profiling of TIMP-2 and Ala+TIMP-2 tumor cells and xenografts demonstrated changes in cell-membrane association of E-cadherin and β-catenin, suggestive of mesenchymal to epithelial (MET) transition." (PMID 29393911, 2018). "It has been reported that EZH2 can attenuate expression of TIMP-2 and TIMP-3 by inducing gene promoter DNA methylation, thereby increasing MMP activity in tumor cells." (PMID 30341286, 2018). "Of which, one study used the percentage of positive cells after IHC to calculate the ratio, and the results showed that with the increase of tumor grade, MMP-2/TIMP-2 rose from 1.00 to 1.18." (PMID 26729052, 2017). "RERG increased the expression of TIMP-2 and inhibited the expression of MMP-2 and MMP-9, providing support for a mechanistic explanation of the inhibition of tumor microvessel growth and size by RERG." (PMID 28659184, 2017). "We then confirmed pro-angiogenic cytokines (IL8 and IL6), TIMP-2, and MMPs (MMP-2 and MMP-9) in the isolated tumor tissues by IHC." (PMID 28659184, 2017). "TIMP2 is an important endogenous inhibitor of MMPs which combines with MMP2 preferentially and can regulate the tumor growth, invasion and angiogenesis by a variety of mechanisms for MMP-dependent or MMP-independent pathways." (PMID 27835587, 2016).
tumor (continued). "Our observations pinpointed the heterogeneity of specific molecular abnormalities in each patient; most noticeably, the TIMP2 and DAPK genes were methylated in almost all samples of tumor and their adjacent margins." (PMID 26363785, 2015). "Next, proteomic assays revealed the presence of ≈150 different proteins, most of which are known tumor supportive factors such as PDGFR-β, TIMP-1, and TIMP-2." (PMID 25669974, 2015). "Tumor biopsies were methylated in 1/5 (20 %), 2/5 (40 %), 4/5 (80 %), and 4/5 (80 %) for CDH1, CDKN2A, DAPK, and TIMP2 genes, respectively." (PMID 26363785, 2015). "Tumor biopsies were methylated in 1/5 (20 %), 2/5 (40 %), 4/5 (80 %), and 4/5 (80 %) for the CDH1, CDKN2A, DAPK, and TIMP2 genes, respectively." (PMID 26363785, 2015). "Here we show that TIMP-2 interaction with MT1-MMP activates AKT by a similar mechanism and provides tumor cells with prosurvival signaling." (PMID 26331622, 2015). "Determined by the end of the experiment, LDP(AE)-TIMP2 at doses of 0.20 mg/kg, 0.35 mg/kg and 0.50 mg/kg inhibited the growth of KYSE150 xenograft by 64%, 76% and 82%, respectively; while LDM inhibited tumor growth by 60%." (PMID 26314845, 2015). "We determined the serum levels and tumor tissue expression of MMP-2 and TIMP-2 in 72 CRC patients in relation to clinicopathological features of cancer as well as the prognostic significance of all variables tested for CRC patients’ survival." (PMID 24395652, 2014). "We found that while expression of MMP-2 and MMP-9 was reduced in Spn4A-expressing tumor cells, mRNA expression levels of TIMP-1 and TIMP-2 was significantly increased." (PMID 24961901, 2014). "In our previous study, the serum levels of MMP-2 and TIMP-2 were significantly lower in CRC patients than in healthy subjects and decreased with tumor stage." (PMID 24395652, 2014). "A positive correlation was observed between VEGFR-2 staining, tumor size and TNM stages and an inverse correlation was identified between TIMP-2 expression and VEGFR-2 levels." (PMID 24527080, 2014). "In situ hybridization of tumor tissues demonstrated that TIMP-1 and TIMP-2 were expressed at elevated levels in the stroma of low Gleason score tumors, but were negative in higher Gleason score tissues (GS 8–10)." (PMID 24978435, 2014). "An imbalance between the proteolytic activity of MMP2 and TIMP2 is responsible for degradation of extracellular matrix (ECM) components, and plays a crucial role in tumor invasion and in metastasis formation." (PMID 24083576, 2013). "Results were evaluated in regard to tumor recurrence and indicated that MMP-9 and TIMP-2 were strongly expressed in tumors that displayed recurrence compared with those that did not." (PMID 22852097, 2012). "TIMP-1, TIMP-2, and TIMP-3 are widely investigated members of this family involved in tumor progression and metastasis in a variety of human cancers." (PMID 22547956, 2011). "In the current study, we revealed that the PCs can also control the activity of MMP-2 by acting on the expression levels of MMP-2 inhibitors TIMP-1 and TIMP-2 and the levels of uPAR and PAI-1 in tumor cells." (PMID 20404912, 2010). "Our data revealed that both tumor MMP2 activity (Figure 4A1) and MMP2 (Figure 4A2) and VEGF protein levels were significantly down-regulated in treatment groups, whereas TIMP2 levels were up-regulated when compared to the controls." (PMID 20969807, 2010). "Whole tumour and parenchymal samples demonstrated differential gene expression, with 289 genes significantly overexpressed in the whole tumour, many of which were consistent with stromal gene expression (e.g., COL6A3, COL1A2, POSTN, TIMP2)." (PMID 19401702, 2009). "It is intriguing that TIMP-2 up-regulates NF-κB activity, whereas TIMP-2-overexpression can prevent tumor invasion." (PMID 19627587, 2009).